CGAS (cyclic GMP-AMP synthase)
Diseases named in the same sentence as CGAS in open-access papers (continued):
Sharing a sentence is not in itself a finding about the gene and the disease.
cancer (continued). "However, the specific role of the cGAS-STING pathway in chemoresistant cancer cells, as well as how cancer cells adapt and survive to the continuous accumulation of cytosolic DNA derived from chemotherapy treatment or chromosomal instability, remains to be elucidated." (PMID 39177280, 2024). "Furthermore, ST-401 could also help the immune response against cancer cell activating the cGAS-STING pathway." (PMID 38730481, 2024). "cGAS is a membrane (inner plasma membrane leaflet)-bound cytosolic protein/enzyme that quickly recognizes invading DNA viruses or the DNA released from an adjacent dying cell, such as cancer cells and DNA contained in the extracellular vesicles (EVs) entering the cell via endocytosis." (PMID 38339107, 2024). "Therefore, cGAS-STING agonists could be used alone or in combination with other drugs to treat various cancers." (PMID 38999073, 2024). "In the future, the functional transformation mechanism of the cGAS–STING signaling pathway in cancers will continue to be further studied, which will provide theoretical support for the study of the pathogenesis of cancer and the therapeutic effect targeting cGAS–STING signaling pathway." (PMID 38525112, 2024). "In addition, cGAS activity in neoplastic cells may accentuate cancer cell sensitivity to DNA damage during radiation/chemotherapy." (PMID 38226619, 2024). "Interestingly, the cGAS/STING pathway is frequently suppressed in a variety of cancers." (PMID 37888903, 2023). "Here, we questioned whether DNA‐PK may be involved in genotoxic stress‐associated type I IFN responses in cancer cells that do not express detectable cGAS levels." (PMID 36574362, 2023). "In addition, the cGAS-STING pathway is responsible for the innate immune recognition of cancer." (PMID 37355491, 2023). "However, it is crucial to note that the activated cGAS-STING pathway might also exhibit pro-cancer functions under specific conditions." (PMID 37448962, 2023). "Cytoplasmic chromatin fragments (CCFs) formed in the cytoplasm during multiple models of senescence activate the cGAS-STING (cyclic GMP-AMP synthase linked to a stimulator of interferon genes) pathway, an intracellular immune system that promotes SASP secretion, especially in cancer cells." (PMID 37543653, 2023). "Thus, activating cGAS by self-DNA can carry out multiple functions in cancers." (PMID 37834184, 2023). "cGAS and STING were analyzed in human cell lines and tissue samples from different types of cancer without important genome mutations, but, interestingly, the cGAS-STING pathway is often suppressed in a variety of cancers by epigenetic mechanisms involving DNA hypermethylation." (PMID 40778061, 2023). "However, we also find that Pxl stimulates, in a cGAS-dependent fashion, upregulation of the expression of the immune checkpoint protein PD-L1 in cancer cells that, on the other hand, may favor cancer cell evasion form immunosurveillance." (PMID 36960066, 2023). "Importantly, the same report claimed that Mn2+ itself may serve as a potent cGAS activator independently of the presence of dsDNA, hence forcing cancer cells to produce type I IFNs." (PMID 38139802, 2023). "Moreover, the suppression of the cGAS-STING pathway found in cancer cells could be another factor leading to the lack of production of the M1 phenotype-related cytokines in the B16-F10 cells upon treatment with the DMXAA formulations." (PMID 40838054, 2023). "However, many other studies have revealed that cGAS activation by self-DNA could promote cancer development by inducing chronic and aberrant inflammation." (PMID 37834184, 2023).
cancer (continued). "Moreover, prior study indicates that ATM deficiency activates cGAS/STING through promoting cytoplasmic leakage of mitochondrial DNA, and subsequently induces type I interferon (T1IFN)-mediated innate immune response in certain cancer types 21,22." (PMID 36778120, 2023). "Thus, if the Pxl-activated cGAS/STING pathway would increase PD-L1 expression in cancer cells, this might promote, on the other hand, cancer cell escape from surveillance by the adaptive immune system." (PMID 36960066, 2023). "However, a pan-cancer analysis has demonstrated that elevated activation of the cGAS-STING pathway, particularly of IRF3, is associated with poor prognosis in patients diagnosed with specific types of cancer, including colorectal, prostate and lung adenocarcinomas." (PMID 38203626, 2023). "However, it remains largely unknown how intra-tumoral cGAS/STING signaling is suppressed to facilitate the immune evasion of cancer cells." (PMID 37193698, 2023). "Furthermore, the cGAS-STING pathway is involved in cancer metastasis." (PMID 36936940, 2023). "Interestingly, metformin was also reported to activate the cGAS–STING pathway in cancer cells." (PMID 37760436, 2023). "However, the role of cGAS in cancer cells remains to be elucidated." (PMID 35563740, 2022). "Therefore, for cancers loss of cGAS-STING function, oncolytic virus is prospective in combating this immune evasion, and the therapeutic effects can be predicted by measuring expressional levels of cGAS or STING in biopsy specimens." (PMID 36588690, 2022). "Indeed, cGAS-STING is an important pathway in cancer immunotherapy." (PMID 36221123, 2022). "The positive cells of senescence-associated β-galactosidase staining and cGAS, STING, interferon-regulatory factor 3 (IRF3), and signal transducer and activator of transcription 6 (STAT6) expression levels using immunostaining were elevated in HGD and in cancers." (PMID 36061145, 2022). "In addition, we show that Top1 poisons can activate both IRF3- and NF-kB-dependent genes, however, they cannot in SCLC cancer cells as the cGAS-STING pathway is markedly impaired likely due to several mechanisms including a drastic reduction of STING and/or cGAS expression." (PMID 35794238, 2022). "Interestingly, similar results as far as lack of type 1 IFN response were found using ATRi and WEE1i, indicating that context such as cancer type may affect the ability of DDRi to induce the cGAS/STING pathway." (PMID 36276148, 2022). "In addition to the originally identified role of cGAS as a response to pathogens, recent studies have shown the importance of the cGAS pathway in cancer therapy, via the induction of antitumor immunity, and the relationship between cGAS levels and the prognosis of cancer patients." (PMID 35563740, 2022). "Therefore, cGAS-STING agonists have been used in the treatment of cancers." (PMID 35692503, 2022). "In addition to the genome, the mitochondria in cancer cells contribute to cGAS-STING activation." (PMID 35741087, 2022). "Therefore, specific activation of the cGAS-STING signaling pathway in ALT-induced cancers may become a new therapeutic option." (PMID 35185917, 2022). "In particular, the role of cGAS in the response of cancer cells to treatment remains unclear." (PMID 35563740, 2022). "Despite the deficiency in the cGAS receptor, the injection of WGP (a commercially available S. cerevisiae glucan) or the in-house extract of glucan inhibited the growth of subcutaneous tumors in cGAS-/- mice suggested that non-cGAS-mediated anti-cancer mechanisms are associated with beta-glucan." (PMID 36142859, 2022). "However, the expression and function of cGAS in cancer cells are not fully understood." (PMID 35563740, 2022).
cancer (continued). "In breast-cancer susceptibility gene 2 (BRCA2)-deficient cancer cells, the inactivation of replicative stress response factors (e.g. poly (ADP-ribose) polymerase [PARP1] or ATM and Rad3-related [ATR] inhibition) triggers cyclic GMP-AMP synthase (cGAS)-STING-mediated innate immune responses." (PMID 34970273, 2021). "Specifically, the nuclear-localization of cGAS has essential significance in cancer progression and therapy, tumors with high tolerance to DNA damage may provide a permissive microenvironment for nuclear cGAS to respond to the genotoxic stress to exert its tumorigenic effects." (PMID 37305397, 2021). "Thus, it is plausible that cGAS gene alternations may contribute to cancer phenotypes; however, more in-depth investigations are warranted to examine this concept." (PMID 33927185, 2021). "From this point of view, the activation of the cyclic GMP–AMP synthase (cGAS)–stimulator of interferon genes (STING) pathway to induce an inherent type I interferon (IFN) response has received increasing attention as the next generation of cancer immunotherapy." (PMID 35052713, 2021). "By analogy, FTI treatment causes mitotic stress leading to cGAS-STING signaling, which might explain the dose-dependent FTI decrease in cell growth and promotion of SNS as observed in different cell types including cancer cells." (PMID 34299092, 2021). "Thus during conditions (exposure to ionic radiations) responsible for cellular senescent, the chromatin DNA in the cytosol induces cGAS-STING signaling to cause short-term inflammation for restraining activated oncogenes that promote tissue destruction and cancer." (PMID 33643304, 2020). "Thus, cGAS and STING intact human epithelial cancer cells can sense cytosolic DNA through the cGAS–STING signaling pathway, and there may be novel pathways and molecules to control the production and secretion of IFN-β." (PMID 33490069, 2020). "Multiple studies showed that radiation-induced DNA damage causes the formation of micronuclei that then activate the cGAS-STING pathway.61–65 To study whether cGAS activation in irradiated cancer cells contributes to antitumor immunity, the abscopal effect of radiation was investigated." (PMID 32541866, 2020). "Recently, a series of publications indicated that IFN-I secretion following RT might be initiated by cancer cells themselves responding to cytosolic DNA fragments activating cGAS/STING, a process negatively regulated by activation of the DNA exonuclease Trex119–21." (PMID 32355214, 2020). "Therefore, the cGAS-STING pathway may serve as a pivot linking cancer and immunity, which triggered researchers to explore the role of this pathway in cancer development and its potential in cancer therapies." (PMID 32532954, 2020). "Regardless, these data confirm that cGAS-driven 2′3′-cGAMP export from cancer cells is directly involved in activation of STING signaling in neighboring endothelial cells, prompting us to examine whether it might play additional roles in priming the vasculature to promote immune cell recruitment." (PMID 33013881, 2020). "Interestingly, cGAS-STING activation has been considered as a therapeutic strategy for cancer." (PMID 32477956, 2020). "Previous studies reported that inhibiting DNA damage response proteins (poly-ADP-ribose polymerase (PARP) and checkpoint kinase 1 (CHK1)) could activate cGAS-STING-mediated anti-cancer immunity, and enhance the blockade of PD-1 checkpoint and infiltration of cytotoxic T cell." (PMID 33268765, 2020). "Cancer cells may resist against the activation of the cGAS-STING pathway." (PMID 31695799, 2019). "With this in mind, cGAS-STING activation by DNA bridges may promote cancer immunogenicity." (PMID 30482235, 2018). "The cGAS-STING pathway, a critical cytosolic DNA-sensing mechanism in innate immunity, holds significant promise for cancer immunotherapy." (PMID 41560305, 2026).
cancer (continued). "Together, this study identifies cGAS-STING as a potential predictor of immunotherapy response and highlights a novel therapeutic strategy for restoring innate immune function in cancer." (PMID 40830678, 2026). "The cGAS/STING pathway serves as an upstream signaling hub for IRF7 activation and plays a key role in cancer and inflammatory diseases." (PMID 41164952, 2026). "To confirm this finding at the protein level, we examined cGAS and STING expression levels by immunoblots in a panel of patient-derived ecDNA+ cancer cells." (PMID 41509453, 2026). "In the adjacent tissues surrounding the cancer cells, STING and cGAS expression was almost universally high." (PMID 39967410, 2025). "Targeting the interplay between cGAS-STING and ferroptosis using nanomedicines offers a novel cancer treatment regimen." (PMID 40846966, 2025). "This study established a dual-action paradigm where ferroptosis and cGAS-STING activation mutually potentiate oxidative damage and immune activation, offering a novel strategy for refractory cancer therapy." (PMID 40846966, 2025). "Inside cancer cells, Mn2+ catalyzed the conversion of H2O2 into •OH, triggering CDT and activating the cGAS-STING pathway." (PMID 40365286, 2025). "Targeting ferroptosis or cGAS-STING can synergistically treat diseases involving oxidative stress, chronic inflammation, and cancer." (PMID 40846966, 2025). "Emerging evidence has shown that targeting the interplay between cGAS-STING and ferroptosis using nanomedicine represents a novel therapeutic regimen for cancers." (PMID 40846966, 2025). "Stimulating endogenous IFN synthesis, for example by turning on the cyclic GMP-AMP synthase (cGAS)-stimulator of interferon genes (STING) pathway, is one method of exploiting interferon’s anti-cancer capabilities." (PMID 41181104, 2025). "Radiotherapy of cancer cells generates cytoplasmic dsDNA breaks, which then activate the cyclic GMP–AMP synthase (cGAS)—stimulator of interferon gene (STING) pathway in the cells." (PMID 40230051, 2025). "Our data reveal an unrecognized off-target effect of class A ODN on suppressing the cGAS signaling in FRCs, which should be considered when designing class A ODN regimens for inflammatory diseases and cancer." (PMID 40337520, 2025). "The cGAS-STING pathway, traditionally recognized for antiviral defense, has emerged as a potential target for cancer immunotherapy due to its ability to activate both innate and adaptive immune responses." (PMID 40520004, 2025). "As the mechanistic understanding of cGAS-STING pathway has rapidly advanced in recent years, increasing efforts of anti-inflammatory and anti-cancer therapeutics development are focusing on modulating STING protein." (PMID 39999142, 2025). "Together, these immune cell-targeted strategies provide a robust approach to indirectly activating the cGAS-STING pathway and achieving more effective cancer immunotherapy." (PMID 40052963, 2025). "More recently, pharmacologic manipulation of the cGAS–STING pathway has been proposed as a therapeutic strategy, notably in cancer to render tumors “immunologically hot” as a way to facilitate response to immunotherapies." (PMID 39412947, 2025). "CGAS and STING1 also play essential roles in maintaining genome integrity and the initiation and progression of cancer." (PMID 40463121, 2025). "Combination therapy of cGAS-STING pathway agonists with PD-1/PD-L1 axis blockade represents a novel and promising strategy in the fight against cancers resistant to traditional immunotherapy." (PMID 41007722, 2025). "In the context of NSCLC, overexpression of GSDME leads to mitochondrial damage and activates the cGAS-STING-IFNβ signaling pathway, which promotes CD8+ T cell proliferation and results in favorable anti-cancer effects." (PMID 41291696, 2025).
cancer (continued). "In summary, our results unravel an unrecognized off-target effect of class A ODN on suppressing the cGAS level and signaling in FRC, which provides critical information for designing class A ODN therapies for inflammatory diseases and cancer in the future." (PMID 40337520, 2025). "Researchers have discovered that the cGAS-STING signaling pathway is closely related to the innate immunity against HPV infection and HPV-related cancers." (PMID 41142804, 2025). "In summary, activation of the cGAS-STING pathway in tumors can induce ferroptosis, thereby achieving therapeutic effects against cancer." (PMID 40846966, 2025). "The cGAS-STING axis is vital for tissue homeostasis and host defense, and cGAS-STING dysfunction activates pro-inflammatory signaling pathways, resulting in inflammatory, autoimmune, and degenerative diseases and cancer." (PMID 40846966, 2025). "In this review, we outline the principal components of the cGAS-STING signaling cascade and discuss its role in cancer biology." (PMID 40846966, 2025). "The cGAS/STING pathway is not only important for the defense against pathogens, but also in anti‐cancer immunity, primarily through the secretion of type I IFNs." (PMID 40145387, 2025). "Liu and colleagues discovered that Brivanib acts as a novel synergistic agent for cGAS, significantly enhancing the STING-TBK1-IFN-I response induced by cancer chemotherapy in vitro and in vivo." (PMID 40470467, 2025). "In cancer cells, RT-induced endogenous production of IFN-I primarily relies on the cGAS/STING pathway activated by cytoplasmic dsDNA, boosting cancer immunogenicity and strengthening antitumor immune responses, leading to better treatment outcomes." (PMID 41041344, 2025). "Suppression of cGAS-STING was found in various human malignancies, leading to growing interest in small-molecule agonists that reactivate this pathway to kill cancer." (PMID 40552295, 2025). "Recent studies have revealed that DNA methylation, histone methylation/demethylation, m5C modification, and non-coding RNA (ncRNA)-mediated epigenetic modifications induce the suppression of cGAS and STING in cancer." (PMID 40846966, 2025). "The encapsulation of these agents activates the cyclic GMP-AMP synthase/stimulator of interferon genes (cGAS/STING) pathway, enhancing the immune response against cancer cells." (PMID 40377870, 2025). "A growing body of evidence has shown that cGAS-STING interacts with regulated cell death (RCD), resulting in ferroptosis in cancers." (PMID 40846966, 2025). "Despite clear evidence that SIRT7 inhibits the cGAS–STING pathway across multiple cellular contexts, the relevance of this process to anti-cancer immunity remains largely unexplored." (PMID 41471367, 2025). "In contrast, human cancer cell lines co-expressing functional cGAS and STING exhibit activation of the cGAS-STING pathway (evidenced by TBK1/IRF3 phosphorylation and ISG expression) upon cytosolic DNA sensing yet fail to secrete IFN-β." (PMID 41007720, 2025). "This, in turn, activates the cGAS‐STING innate immune pathway, overcoming cancer resistance to PD‐L1 therapy in a cGAS‐dependent manner." (PMID 39834553, 2025). "As research into the cGAS-STING pathway continues, it holds significant promise for cancer immunotherapy." (PMID 40739089, 2025). "The mitotic progression of cells after genotoxic cancer treatment leads to the formation of MN, which exhibits interferon-stimulated gene (ISG) characteristics dependent on the cGAS-STING pathway." (PMID 41007720, 2025). "We then focus on providing an overview of the latest findings and emerging concepts that leverage the interplay between cGAS-STING and ferroptosis by nanomedicine to kill cancers." (PMID 40846966, 2025). "The cyclic GMP‒AMP synthase-stimulator of interferon genes (cGAS‒STING) pathway, an essential cytosolic DNA sensor that facilitates innate immune responses, has surfaced as a prospective target for cancer immunotherapy." (PMID 41063281, 2025).